LCN2 (lipocalin 2)
Diseases named in the same sentence as LCN2 in open-access papers (continued):
Sharing a sentence is not in itself a finding about the gene and the disease.
Hypercalcemia (1 paper, 2014). An abnormally increased calcium concentration in the blood. "In summary, we demonstrated in this report that vitamin D in a form of dietary supplementation can prevent and suppress ICC tumorigenesis and progression with downregulation of LCN2 in an animal model without inducing hypercalcemia." (PMID 24939880, 2014).
Hyperkeratosis (1 paper, 2025). Hyperkeratosis is a histopathological term defining a thickened stratum corneum and may be present in many different skin conditions, with many possible overlaps. "Additionally, bioinformatic analysis revealed that on day 4 post-transplantation, the immune response was mainly suppressive, suppressing graft hyperkeratosis, which is a characteristic of rejection, and that Lcn2 and Pou2f2 further negatively regulated the immune response." (PMID 41221286, 2025).
hyperphosphatemia (1 paper, 2021). Abnormally high level of phosphate in the blood. "Similarly, the lack of effects of LCN2 on FGF23 in a model of diet-induced hyperphosphatemia suggests that LCN2 does not play a role in phosphate-induced FGF23 production." (PMID 34334787, 2021).
hyperthyroidism (1 paper, 2020). Overactivity of the thyroid gland resulting in overproduction of thyroid hormone and increased metabolic rate. "After PPI network construction, the top five hub genes associated with hypothyroidism were extracted, including ALB, MAPK1, SPP1, PPARG, and MIF, whereas those associated with hyperthyroidism were ALB, FCGR2B, CD44, LCN2, and CD74." (PMID 32500465, 2020). "The top five hub genes associated with hypothyroidism are ALB, MAPK1, SPP1, PPARG, and MIF, whereas those associated with hyperthyroidism are ALB, FCGR2B, CD44, LCN2, and CD74." (PMID 32500465, 2020).
infectious colitis (1 paper, 2014). A viral or bacterial infectious process affecting the large intestine. "To investigate any possible mechanistic differences between the Lcn2−/− and Lcn2+/+ mice during S. Typhimurium infection, we validated several key regulators involved in the pathophysiology of infectious colitis." (PMID 24465207, 2014). "Our data suggest that this crosstalk between Lcn2 and MMP-9 in the inflamed gut, which results in increased MMP-9 activity, was crucial for the deleterious impact on the intestinal mucosa observed during infectious colitis." (PMID 24465207, 2014). "Interestingly, using Lcn2 mutant mice we show that lack of Lcn2 effectively reduced tissue damage and the degree of inflammation, thus supporting a pivotal role of Lcn2 and MMP-9 in infectious colitis." (PMID 24465207, 2014).
interstitial lung disease (1 paper, 2025). A diverse group of lung diseases that affect the lung parenchyma. "Additionally, the elevation of LGALS3 in SS stages suggests its role as an alarmin, particularly in SS patients with interstitial lung disease, and underscores the intricate interplay between LGALS3, LCN2, SS, and TC." (PMID 39928612, 2025).
intestinal tumour (1 paper, 2014). "We thus conclude that LCN2 has a cell- and content-dependent function, which has also been well-documented in the mouse intestinal tumour model APCmin." (PMID 25010215, 2014).
iron (1 paper, 2024). "Because the salmochelin secreted by IroA-E. coli is resistant to the sequestration of LCN2, we speculated that IroA-E. coli could have ameliorated the iron deficiency problem in the TME." (PMID 38747577, 2024).
leukocytosis (1 paper, 2021). "Therefore, increased LCN2 serum protein might be in part a consequence of leukocytosis in these patients." (PMID 34439364, 2021).
leukoplakia (1 paper, 2025). A white patch or plaque on a mucous membrane that cannot be characterized clinically or pathologically as any other disease. "Although our analysis compared OSCC to BC samples, 19 significant genes overlapped with Farah and Fox’s 47 differentially expressed genes (DEGs), including the upregulation of ODC1 and LCN2 and the downregulation of COL1A1, COL11A1, and STAC2 in dysplastic leukoplakia samples." (PMID 40650045, 2025).
malignant glioma (1 paper, 2021). A grade III or grade IV glioma arising from the central nervous system. "Western blot and RT-qPCR analysis of human malignant glioma cell lines (GBM8901, U-87MG, U-251, GBM8401 and M059K) showed that GBM8901, U-87MG, U-251 and M059K cell lines had lower protein and mRNA expression of LCN2 than the GBM8401 cells." (PMID 34062746, 2021).
memory (1 paper, 2024). The activities involved in the mental information processing system that receives (registers), modifies, stores, and retrieves informational stimuli. "Moreover, the Morris water maze demonstrated that rats in the ICH+si-LCN2 group had better spatial learning and memory impairments compared with the ICH group." (PMID 39113700, 2024).
mesenchymal tumor (1 paper, 2008). "The previous report indicated that lipocalin 2 could diminish migration and invasion of 4T1-Ras-transformed mesenchymal tumor cell line." (PMID 19077278, 2008).
morphine dependence (1 paper, 2014). Strong dependence, both physiological and emotional, upon morphine. "Among these DEGs, Lcn2 and Hspb1 participated in the regulation of NF-κB pathway activation, which plays a complex role in morphine dependence." (PMID 25012590, 2014).
neuroblastoma (1 paper, 2022). Neuroblastoma (NB) is the most common solid, extracranial childhood tumor. "In a separate in vitro experiment, we found a marked elevation and secretion of LCN2 protein after application of LPS (a TLR4 activator) on a murine neuroblastoma cell line N2A (data not shown), suggesting the existence of the LCN2 regulation pathway in neurons." (PMID 35413913, 2022).
nevus (1 paper, 2016). Nevus (or naevus, plural nevi or naevi, from nævus, Latin for "birthmark") is the medical term for sharply circumscribed[1] and chronic lesions of the skin or mucosa. "The overexpression of Tcf7l1 and LCN2 in melanocytes of pigmented nevus suggests an additional function of the Tcf7l1–LCN2 axis, which should be elucidated in other studies." (PMID 27551519, 2016).
non-alcoholic fatty liver (1 paper, 2022). A benign form of fatty non-alcoholic fatty liver disease where the disease has not yet progressed to the inflammation of liver. "LCN2 is also upregulated in serum and liver tissue of patients with non-alcoholic fatty liver (NAFL), and serum LCN2 levels could be a novel biomarker for the diagnosis of non-alcoholic steatohepatitis (NASH), which may be participate in the transition from NAFL to NASH by mediating inflammation." (PMID 35495713, 2022).
ocular hypertension (1 paper, 2024). Abnormally high intraocular pressure. "Gene expression of signature astrocyte reactivity markers (Gfap, Lcn2, Steap4, Gbp2, Serping1, and Fbln5) were significantly upregulated in response to ocular hypertension at 2, 4, and 8 weeks compared to that in normotensive controls." (PMID 38610040, 2024).
osteogenesis imperfecta (1 paper, 2024). Osteogenesis imperfecta (OI) comprises a heterogeneous group of genetic disorders characterized by increased bone fragility, low bone mass, and susceptibility to bone fractures with variable severity. "We investigated the correlation of serum LCN2 levels and glycolipid metabolism, and body composition in a large cohort of patients with osteogenesis imperfecta (OI)." (PMID 37326909, 2024).
Ovarian cyst (1 paper, 2019). The presence of one or more cysts of the ovary. "Three proteins (6Ckine, Lipocalin-2, IL-7), on the other hand, were differentially expressed between ovarian cyst patients and healthy controls." (PMID 31333337, 2019).
pneumococcal bacteremia (1 paper, 2023). "LCN2 concentration was associated with pneumococcal bacteremia in the univariate analysis: OR 1.03 (95% CI 1.01–1.05, p = 0.026)." (PMID 37317134, 2023). "The LCN2 cutoff ≥ 204 ng/mL predicted the presence of pneumococcal bacteremia with an AUROC of 0.74 (sensitivity 70%, specificity 79.1%)." (PMID 37317134, 2023).
prion disease (1 paper, 2022). A transmissible disease that is caused by a protein that is able to induce abnormal folding of normal cellular proteins, leading to characteristic spongiform brain changes, which are associated with neuronal loss without an inflammatory response. "Further studies are required to determine whether complement component C3 and LCN2 contribute to the development of the neuropathology in the prion disease‐affected brain, or whether they are simply indicative markers of dysregulated reactive astrocytic activation." (PMID 35852018, 2022).
Rectal prolapse (1 paper, 2019). Protrusion of the rectal mucous membrane through the anus. "Notably, increases relative to WT mice were only observed in active disease (rectal prolapse and/or high Lcn-2)." (PMID 30936879, 2019). "A comparison of WT, Gab2−/−, Gab3−/−, and Gab2/3−/− mice showed that maximal Lcn-2 increase was observed in double knockout mice (average of 26-fold), whereas mice with rectal prolapse had high Lcn-2 levels, but high Lcn-2 levels did not predict rectal prolapse." (PMID 30936879, 2019).
renal osteodystrophy (1 paper, 2024). Abnormalities of bone mineral metabolism associated with chronic kidney disease. "Thus, the regulatory role of LCN2 in renal osteodystrophy is an interesting issue and further investigation is needed." (PMID 39613734, 2024).
retinal detachment (1 paper, 2019). An eye emergency condition which may lead to blindness if left untreated. "The extent of retinal detachment seems to be correlated with the levels of LCN2 (U = 3, p<0.001)." (PMID 31891637, 2019).
retinoblastoma (1 paper, 2025). A malignant tumor that originates in the nuclear layer of the retina. "Among the most upregulated genes were KRT5, KRT19, LCN2, SLP1 and S100A9, while GNAT1, PDE6G, WIF1, FRZB, and RHO were among the top downregulated genes in retinoblastoma." (PMID 40395327, 2025).
Rett syndrome (1 paper, 2024). A severe neurodevelopmental disorder affecting the central nervous system. "Although the exact mechanism of reduced LCN2 expression is still unclear, these findings suggest that LCN2 may be involved in developmental disorders, such as Rett syndrome, and potentially plays a role in developmental abnormalities observed in human hand-reared marmosets." (PMID 38172165, 2024).
silicosis (1 paper, 2022). Silicosis is a respiratory disease caused by breathing in (inhaling) silica dust. "For the first time, we found that cellular adhesion molecules (CAM), such as Gm2a, CHI3L1, LCN2, THBD, NADPH oxidase (NOXs) and vacuolar-ATPase are involved in pathogenesis of silicosis." (PMID 34991559, 2022).
skin papilloma (1 paper, 2017). A benign papillary neoplastic growth on the skin composed of epithelial cells and a fibrous stalk. "We showed that overexpression of TCF7L1 induced expression of LCN2 in vivo as previously reported and that expression of LCN2 was also induced in murine skin papilloma and SCC similarly to TCF7L1." (PMID 28467300, 2017).
staphylococcus aureus infection (1 paper, 2019). An infectious process in which the bacteria Staphylococcus aureus is present. "Notwithstanding, increased levels of Lcn2 were observed in patients with Staphylococcus aureus infection (bacterium whose siderophores are unrecognizable by Lcn2) or Streptococcus pneumoniae (bacterium that does not express any siderophores)." (PMID 31375129, 2019).
Streptococcus pneumonia (1 paper, 2023). "In contrast, LCN2 impairs immune responses and bacterial clearance of Streptococcus pneumonia and increases mortality." (PMID 36923935, 2023).
thyroid nodule (1 paper, 2018). A small circumscribed mass in the THYROID GLAND that can be of neoplastic growth or non-neoplastic abnormality. "Our results indicate that LCN2 expression may also serve as a useful biomarker in DTC, namely for the FNAB diagnosis of thyroid nodules." (PMID 29321030, 2018).
urinary tract obstruction (1 paper, 2016). Blockage of the normal flow of contents of the urinary tract. "For example, the more glycosylated urinary LCN2 isoform could be useful for predicting urinary tract obstruction." (PMID 26949374, 2016). "However, the relationship between urinary tract obstruction and the isoform diversity of LCN2 has not been examined." (PMID 26949374, 2016).
uterine cancer (1 paper, 2019). Primary or metastatic malignant neoplasm involving the uterine corpus and/or the cervix. "LCN2 may indirectly be associated with uterine cancer, mediated by IL-8 secretion." (PMID 31151292, 2019).
vascular brain injuries (1 paper, 2020). "Here, we investigated the potential of cerebrospinal fluid (CSF) lipocalin 2 (LCN2), a secreted glycoprotein that has been suggested as mediating neuronal damage in vascular brain injuries." (PMID 32001681, 2020).
ventricular tachycardia (1 paper, 2022). A disorder characterized by an electrocardiographic finding of three or more consecutive complexes of ventricular origin with a rate greater than a certain threshold (100 or 120 beats per minute are commonly used). "Neutrophils increased ventricular tachycardia via lipocalin-2 in mice, whereas neutrophilia associated with ventricular tachycardia in patients." (PMID 36034743, 2022).
Ventriculomegaly (1 paper, 2023). An increase in size of the ventricular system of the brain. "In a mouse model of adult IVH, intraventricular hemoglobin induced Lcn2 upregulation and ventriculomegaly where Lcn2-deficient mice were protected against hemoglobin-induced ventricular dilation, glial activation, and mortality." (PMID 38283681, 2023).
α-synucleinopathies (1 paper, 2025). "The identification of LCN2/24p3R as a key regulator of α-Syn by astrocytes provides a new target for the treatment of PD and related α-synucleinopathies." (PMID 40686313, 2025).
tumor (391 papers, 2002 to 2026). "Cancer cells exploit the iron-transporting capability of LCN2 by inducing macrophages to secrete high levels of LCN2-bound iron, a mechanism linked to tumor formation, metastasis and recurrence in BC patients." (PMID 41303420, 2025). "This is consistent with the observation that LCN2 can promote invasion and angiogenesis and is associated with metastasis in multiple tumor types." (PMID 40356520, 2025). "While elevated LCN2 levels in serum or tumor tissue have been proposed as diagnostic or prognostic biomarkers in BC, there are no standardized thresholds, detection methods or prospective clinical trials validating its utility in TNBC." (PMID 41303420, 2025). "This will provide a new template for the future optimization of LCN2-associated tumor therapeutic structures." (PMID 39852526, 2025). "On the one hand, an increase in the intracellular iron level caused by LCN2-mediated endocytosis elevates the ROS level, which, in turn, increases genetic instability and promotes tumor progression." (PMID 40109857, 2025). "Although many studies report its association with aggressive tumor behavior, the mechanistic understanding of how LCN2 contributes to TNBC progression, metastasis and therapy resistance is still limited." (PMID 41303420, 2025). "Higher neutrophil counts were associated with increased LCN2 expression, which increased with advancing tumor stage." (PMID 41303420, 2025). "Elevated LCN2 expression has been associated with ferroptosis resistance, increased tumor aggressiveness, and poor clinical outcomes in various cancers, suggesting its potential relevance in OS pathophysiology." (PMID 40636695, 2025). "Further analysis of TCGA‐STAD samples showed that higher LCN2 expression was associated with reduced tumor infiltration of M2‐type TAMs and increased tumor infiltration of M1‐type TAMs." (PMID 40884261, 2025). "These are Ccl4+Cd274+Lcn2+Ptgs2+ immunosuppressive neutrophils implicated in EMT induction in tumor cells." (PMID 40568084, 2025). "For instance, in inflammatory breast cancer, augmented levels of LCN2 reportedly promote tumor aggressiveness by regulating cell cycle-associated proteins and are correlated with a poor prognosis." (PMID 40313933, 2025). "Elevated MCT2 (SLC16A7) levels were associated with increased expression of interleukin-1β (IL-1β) and lipocalin-2 (LCN2), both of which are linked to tumour progression and adverse outcomes." (PMID 41154605, 2025). "Elevated LCN2 levels have been observed in fibroblasts, endothelial cells, and tumor-associated macrophages (TAMs), reinforcing its role in TME regulation." (PMID 40472740, 2025). "Taken together, the molecular mechanisms involved in the oncogenic and tumor-suppressive roles of LCN2 are associated with EMT, iron metabolism, the LCN2/MMP9 complex, and angiogenesis." (PMID 40109857, 2025). "LCN2, originally found in neutrophils and kidney cells, is implicated in tumor invasion, immune suppression, and ECM degradation in various cancers, including thyroid, prostate, lung, liver, and OSCC." (PMID 40472740, 2025). "LCN2, which regulates inflammation and immune response in the tumor microenvironment, is overexpressed in aggressive TC variants and is associated with epithelial-mesenchymal transition, making it a valuable predictive and diagnostic biomarker." (PMID 39928612, 2025). "Since LCN2 inhibits ferroptosis in CRC cells by decreasing intracellular iron levels and stimulating the expression of GPX4 and xCT, elevated levels of LCN2 are associated with tumor progression and drug resistance." (PMID 39359721, 2024). "Elevated expression of LCN2 has been observed in various types of cancer and is implicated in different aspects of tumour progression." (PMID 39021353, 2024). "A large number of studies suggest that LCN2 is a carcinogenic protein implicated in tumour initiation, advancement and metastasis." (PMID 39021353, 2024).